MTOR (mechanistic target of rapamycin kinase)
Diseases named in the same sentence as MTOR in open-access papers (continued):
Sharing a sentence is not in itself a finding about the gene and the disease.
Hyperglycemia (continued). "Furthermore, the amount of total and phosphorylated mTOR, which is directly correlated with glucose metabolism, and CD39+ Tregs, representing the metabolism of ATP into immunomodulatory adenosine, also dropped along with CTLA-4-positive Tregs in hyperglycemia." (PMID 41597269, 2026). "Hyperglycaemia, instead of hyperinsulinaemia and hyperlipidaemia, can significantly induce the expression of SARS‐CoV‐2 entry factors in the liver, but not in the lung and pancreas, which is attenuated by the inhibition of mechanistic target of rapamycin kinase (mTOR)." (PMID 40442985, 2025). "Hyperglycemia in cultured rat endothelium led to the upregulation of DNMT1 expression, the suppression of Meg3, and the expression of proteins consistent with the endothelial-mesenchymal transmission and the activation of the mammalian target of rapamycin (mTOR) pathway." (PMID 36833344, 2023). "In general, treatments with D3T under hyperglycemia showed a greater induction in the relative expression of IL-10 compared to that treated with RSV, suggesting that regulation under Nrf2 stimulation could be more efficient than mTOR induction." (PMID 37630249, 2023). "Rhein could inhibit autophagy by regulating AMPK-dependent mTOR signaling pathways and Erk and p38 MAPK signaling pathway; it protects pancreatic β-cells against apoptosis by blocking hyperglycemia-induced dynamin-related protein 1 (Drp1) expression and stabilizing mitochondrial morphology." (PMID 35431942, 2022). "Nonfasted hyperglycemia was also evident in mTOR-KOPlacenta compared with littermate controls." (PMID 34032632, 2021). "Because we did not include a group of animals treated with a specific Akt inhibitor nor studied other pathways including the hexosamine or Akt-mTOR system the exact of role of Akt as a mediator of insulin-pre-conditioning and hyperglycemia remains to be determined." (PMID 28376800, 2017). "However, saturation of glucose uptake in mesangial cells has been reported to occur at 30 mM, indicating that hyperglycaemia can induce mTOR in the absence of increased GLUT1 expression." (PMID 26464852, 2014). "Finally,blockade of the mTOR cascade reduced hyperglycemic damage also in a morepathophysiologically relevant model, i.e. in human umbilical veinendothelial cells (HUVEC) exposed to hyperglycemia." (PMID 20739737, 2010). "Taken together, these findings in tissue-specific cells show that hyperglycemia converges on major insulin, lipid, and fibrosis pathways by DNA methylation to regulate the expression of core genes that consist of but are unlikely to be limited to MTOR, RPTOR, IRS2, TXNRD1, LCAT, SMPD3, and COL1A2." (PMID 36633903, 2023). "Interestingly, hyperglycemia-induced miR-22 promotes EMT by suppressing autophagy via targeting phosphatase and tensin homolog/protein kinase B (Akt)/mTOR signaling pathway, which suggests that targeting miRNA may be a promising therapeutic approach in preventing DN." (PMID 37020591, 2023). "Restoration through AMPK activation or mTOR inhibition could improve mitophagy activity, decrease ROS production and improve MMP in NRK-52E cells, suggesting AMPK/mTOR pathway was directly involved in the regulation of mitophagy inhibited by acute hyperglycemia induced tubular injuries." (PMID 33424763, 2020). "Podocyte apoptosis in the setting of hyperglycemia occurs through mechanisms that include, but are not limited to, increased ROS, RAAS activation, and upregulation of the mammalian target of rapamycin (mTOR) pathway." (PMID 34211943, 2021). "However, the recognition of relevant side-effects in transplanted patients treated with rapamycin, such as hyperglycemia, insulin resistance, and dyslipidemia, may explain the scarceness of preclinical studies and lack of clinical trials using mTOR inhibitors to prevent or modify DN course." (PMID 30510618, 2018).
Hyperglycemia (continued). "This hypothesis might explain why hyperglycemia does not occur in TSC patients, because the pathophysiological hyperactivation of mTORi in these patients is modulated by mTOR inhibition." (PMID 35804402, 2022). "The actions of insulin on glucose metabolism are mediated by PI3K so it is not surprising that in clinical trials, hyperglycemia was a common effect of many early pan PI3K inhibitors, as well as dual-specificity PI3K/mTOR inhibitors and PI3Kα-specific inhibitors." (PMID 31443495, 2019). "Here, we demonstrate that hyperglycemia clearly increases proliferation of both non-tumorigenic and malignant mammary epithelial cells and this is accomplished by increased leptin signaling and pro-survival AKT/mTOR signaling." (PMID 24260287, 2013). "Hyperglycaemia, instead of hyperinsulinaemia and hyperlipidaemia, can significantly induce the expression of SARS‐CoV‐2 entry factors (Ace2, Tmprss2, Tmprss4, Furin and Nrp1) in liver cells, but not in lung and pancreatic cells, which is attenuated by mTOR inhibition." (PMID 40442985, 2025).
depression (223 papers, 2011 to 2026). "Since Gfap and PSD-95 levels are often reduced in depression, and mTOR/EEF2 pathways are implicated in psychiatric disorders, these data further support lurasidone’s neuroprotective profile." (PMID 40141736, 2025). "The mTOR pathway is closely associated with the manifestation of depression-likebehaviors, including anxiety, depressive symptoms, and neuronal atrophy.TrkB, a functional receptor for BDNF, is activated by BDNF, inducing thePI3K/Akt/mTORC1 cascade." (PMID 40071363, 2025). "Abnormal activity of the mTOR pathway causes various neurological and psychotic disorders, including depression and schizophrenia." (PMID 38365306, 2024). "Evidence from animal models and human postmortem brain tissues indicates that depression is associated with a reduction in the PI3K/Akt/mTOR signaling in brain regions like the prefrontal cortex (PFC) and amygdala." (PMID 38926475, 2024). "Recently, microbiota-derived tryptophan metabolism and AMPK/mTOR pathway were found to be strongly linked to the development of depression." (PMID 39351096, 2024). "In the research, we first verified the critical role and regulatory function of SHD by microbiota-derived tryptophan metabolism and AMPK/mTOR pathway of autophagy in improving depression-like behaviors and revealed its associated molecular mechanism." (PMID 39351096, 2024). "Intracellular signaling pathways in the brain involving ERK1/2, GSK3β and mammalian/mechanistic target of rapamycin (mTOR) have been implicated in depression in humans and in antidepressant response in animal models." (PMID 37775532, 2023). "The BDNF-TrkB signaling pathway, as well as the downstream kinases Akt and ERK and the mTOR pathway, have been implicated in depression and neuroplasticity." (PMID 37047730, 2023). "Loss of Phf8 only confers resistance to depression-like and anxiety-like behaviors in mice and causes deficient learning and memory by epigenetic disruption of mTOR signaling." (PMID 36672913, 2023). "A common SNP of BDNF, rs62265, is a missense mutation that has been associated with anxiety, major depression, suicide, and neurodegenerative disease, as has dysregulation of mTOR signaling." (PMID 35444632, 2022). "This is intriguing because previous studies have reported the potential implications of Rai14 in the BDNF and mTOR pathways, which are critical processes for depression-associated synaptic remodeling." (PMID 35467532, 2022). "This study only detected the key proteins in mTOR and pyroptotic cell death pathways to explain the mechanism of anxiety and depression caused by H. pylori." (PMID 35677839, 2022). "PI3K/Akt/mTOR pathway is implicated in modulation of hippocampal activities that result in long-term depression." (PMID 34122166, 2021). "Changes in the activity of various signaling processes such as BDNF, NMDA, and mammalian target of rapamycin (mTOR) are possible mechanisms that underlie alterations of synaptic plasticity leading to depression." (PMID 34064233, 2021). "Recently, PI3K/Akt/GSK-3β/mTOR signaling pathway has been associated to neurobiology of depression and seems to be modulated by some pharmacological antidepressant strategies." (PMID 34790666, 2021). "mTOR functions as a serine/threonine protein kinase which promotes synthesis of lipids, nucleotides and proteins, and it also comprises part of the larger PI3K/AKT/mTOR pathway, which is associated with neuropsychiatric disorders such as depression and ASD." (PMID 34680906, 2021). "Previous studies have reported an association between mTOR and depression, but few investigations of this have occurred in transplant recipients." (PMID 32424120, 2020). "Among the representative pathways obtained from the up-regulated microRNAs, the DIANA Tools software identified the mTOR signaling pathway (p = 0.05), which has been dysregulated and associated with synaptic protein deficits in patients with depression." (PMID 31125682, 2019).
depression (continued). "The finding that rapamycin reduces depression-like behavior contrasts with previous studies indicating that reduced mTOR signaling is associated with depression." (PMID 29686643, 2018). "An increasing number of human diseases have been linked to dysregulation of mTOR, including depression." (PMID 30072893, 2018). "Previous studies showed a loss in mTOR signaling in the hippocampus of subjects with depression and anxiety disorders." (PMID 30089868, 2018). "Dysfunction of the PI3K-AKT/mTOR signaling has been associated with various psychiatric disorders, including depression and anxiety, and the antidepressant actions of some fast-acting and long-lasting antidepressants, such as ketamine, require the activation of the mTOR pathway." (PMID 40141416, 2025). "Therefore, in this review, we have highlighted research outlining the underlying mechanisms of mTOR signaling in depression and the relationship between mTOR signaling and antidepressant drugs." (PMID 38365306, 2024). "Moreover, we have also discussed research indicating that the dysregulation of the mTOR signaling cascade is associated with neurodevelopmental disorders, which would, in turn, lead to depression." (PMID 38365306, 2024). "Depression is caused by synaptic protein defects induced by abnormal mTOR signalling." (PMID 36737776, 2023). "We demonstrated a novel mechanism of gut microbiota in causing depression; gut microbiota cause changes in phosphorylation of the PI3K/Akt/mTOR pathway, which mediates microglial activation and subsequent inflammation, eventually causing the development of depression." (PMID 35713215, 2022). "Depression is caused by synaptic protein defects induced by abnormal mTOR signaling." (PMID 33584387, 2021). "Stress causes reduction of brain derived neurotrophic factor (BDNF) expression and the mechanistic target of rapamycin (mTOR) in synapse, consequently contributing to the loss and atrophy of specific synapse in the brain regions implicated in depression, particularly the PFC and the hippocampus." (PMID 29896088, 2018). "Furthermore, mTOR signaling in depression is downregulated and this deficiency was effectively rescued by ketamine." (PMID 30233424, 2018). "A-amino-3-hydroxy-5-methyl-4-isoxazolepropionic acid (AMPA) receptor and subsequent mammalian target of rapamycin (mTOR) signaling is responsible for synaptic maturation and may contribution to the synaptic alteration underlying depression." (PMID 29609584, 2018). "Here, we tested whether alterations in NMDA receptors and associated mTOR signaling in the PFC are part of the pathology of depression and are part of the therapeutic responses to antidepressant actions of ketamine and Yueju using a CMS mouse model." (PMID 26315757, 2015). "Consistent with previous studies, mice stressed by DEXA injection in the current study had significantly higher pAKT protein expression than normal mice, supporting the hypothesis that depression, which is associated with many factors, activates mTOR, leading to a decrease in autophagy." (PMID 36979839, 2023). "However, causality between mTOR and depression has yet to be determined." (PMID 34445375, 2021). "Therefore, PI3K/Akt/mTOR pathway is associated with depression." (PMID 34122166, 2021). "Therefore, it is reasonable to assume that restoring the Akt/mTOR/p70S6K pathway could be the cause of improvement in the progression of depression." (PMID 34249519, 2021). "The FoxO and mTOR signaling pathways may be involved in the underlying mechanism of the antidepressant effects of ketamine, and Plin4, Sgk1, Klf2 and Dcaf12l1 may be potential biomarkers for depression in N-methyl-D-aspartic acid receptor antagonist treatment." (PMID 31281445, 2019). "Therefore, AMPA receptor-mTOR signaling pathway may be involved in the synaptic alteration underlying depression." (PMID 29609584, 2018).
depression (continued). "Thus, some studies hypothesize that depression results from deficits in synaptic proteins that are caused by abnormalities in mTOR signaling." (PMID 26522512, 2015). "It has been demonstrated that upregulated mTOR expression levels in the prefrontal cortex are likely to be associated with the mechanisms of antidepressant effects, which facilitate the return of the depression-induced atrophic neurons to normal morphology and function." (PMID 24396420, 2014). "Several murine models of depression show reduced hippocampal levels of mTOR, PSD95, and synapsin l, which are restored by antidepressant drug treatments, such as serotonin selective reuptake inhibitors (SSRIs), ketamine, and others." (PMID 40405318, 2025). "We also explored the antidepressant mechanism of NAc-DBS and found that it exerted antidepressant effects and cognitive improvement in a CUMS-induced depression-like mouse model through the activation of BDNF/AKT/mTOR signaling pathway." (PMID 41234534, 2025). "Several proteins related to neuroplasticity processes have been found to be altered in major depression and animal models of depression, and restored by antidepressant drugs, including mTOR, PSD95, BDNF and synapsin I." (PMID 40405318, 2025). "Inhibition of the mTOR pathway blocked synaptogenesis and prevented the antidepressant effects of ketamine in depression models." (PMID 41286527, 2025). "In models of depression, the antidepressant effects of certain drugs, especially rapid-acting drugs such as ketamine, are significantly reduced when an mTOR inhibitor (e.g., rapamycin) is administered." (PMID 41286527, 2025). "The dysregulation of BDNF and p‐mTOR molecules within the BNDF‐mTOR signaling pathway in the hippocampus and prefrontal lobes is believed to play a crucial role in the pathophysiology of depression." (PMID 38332552, 2024). "The mTOR signaling cascade plays important roles in depression and antidepressant drug activity, and activating or enhancing mTOR signaling has been demonstrated to have antidepressant effects in preclinical studies." (PMID 38365306, 2024). "Preclinical studies have reported that the rapid antidepressant response to ketamine and paroxetine is mediated via the activation of the mTOR pathway in animal models of depression." (PMID 38365306, 2024). "In contrast, treadmill exercise combined with a high-fat diet effectively ameliorates depression-like behavioral phenotypes by improving hippocampal synaptic plasticity, which depends on Wnt5a/CamkII/mTOR signaling pathway-mediated autophagy activation." (PMID 39389946, 2024). "So far, few studies have explored the link between tryptophan metabolism in gut microbiota and AMPK/mTOR pathway of autophagy during the pathology of depression." (PMID 39351096, 2024). "The activation of the PI3K-Akt-mTOR signaling pathway contributes to the neurodevelopment of the cerebral neocortex and alleviates depression-like phenotypes." (PMID 38365306, 2024). "To further study the underlying molecular mechanism of autophagy dysfunction in depression, we examined the interaction between NLRP1inflammasome and PI3K/AKT/mTOR signaling pathway." (PMID 38178196, 2024). "Oleanolic acid produced antidepressant‐like effects in mice exposed to chronic stress, while decreased SGK1 and activated BDNF‐AKT/mTOR signaling in the hippocampus in an animal model of CORT‐induced depression." (PMID 37905694, 2024). "Dysregulation of mTOR signalling has been directly associated with MDD, and pharmacological modulation of this pathway shows promise as a treatment for depression." (PMID 39457495, 2024). "In summary, the Wnt5a/CamkII/mTOR signaling pathway identified in this study provides new insights into how exercise alleviates HFD-induced depression-like behaviors." (PMID 39389946, 2024).